MYC (MYC proto-oncogene, bHLH transcription factor)
Diseases named in the same sentence as MYC in open-access papers (continued):
Sharing a sentence is not in itself a finding about the gene and the disease.
Lymphadenopathy (2 papers, 2008 to 2018). Enlargement (swelling) of a lymph node. "The recipient mice were held for observation until they developed externally obvious lymphadenopathy (approximately 100 d for the Eμ-MYC tumors, 58 d for the Eμ-MYC/BCRHEL tumors, 21 d for the Eμ-MYC/BCRHEL/sHEL tumors, and 14 d for the MMTV-rtTA/TRE-MYC/BCRHEL/sHEL tumors)." (PMID 18578569, 2008).
monocytic leukemia (2 papers, 2020 to 2021). "Interestingly, they found a low c-MYC expression level in acute monoblastic/monocytic leukemia, whereas in our study a relatively high c-MYC expression was often noted in the M5 subtype." (PMID 33170359, 2020).
mucosal melanoma (2 papers, 2022 to 2024). A melanoma that arises from a mucosal site. "As in human mucosal melanomas, canine mucosal melanomas show a conserved deletion and insertion event on CFA 30 (HSA 15 in human melanoma), gain of c-MYC, and deletion of CDKN2A [LOE 4a-5, OEG A]." (PMID 38645640, 2024).
multiple sclerosis (2 papers, 2017 to 2019). A progressive autoimmune disorder affecting the central nervous system resulting in demyelination. "MYC has been identified as one of the core transcriptional factors for TH17 differentiation, and a polymorphism close to the MYC genomic locus has been linked to multiple sclerosis susceptibility in human patients." (PMID 28245597, 2017).
neuropathy (2 papers, 2013 to 2015). A disorder affecting the nervous system that manifests with pain, tingling, numbness, and/or muscle weakness.
NK/T-cell lymphoma (2 papers, 2020 to 2024). "It has recently been reported that overexpression of MYC and BCL2 predicts a poor prognosis in patients with extranodal NK/T-cell lymphoma (NKTL) of the nasal type." (PMID 38918775, 2024).
nonalcoholic steatohepatitis (2 papers, 2011 to 2019). "Hepatitis virus-dependent and alcohol-dependent HCC display overexpression of MYC, whereas nonalcoholic steatohepatitis may evolve into malignancy via a MYC-independent mechanism, indicating that the existence of genetic discrepancies may occur via different aetiological routes." (PMID 21955323, 2011).
paraganglioma (2 papers, 2017 to 2026). A benign or malignant neoplasm arising from paraganglia located along the sympathetic or parasympathetic nerves. "In addition, although the exact mechanism by which mutations in MAX lead to paraganglioma development is unknown, these tumors exhibit an elevated expression of the MYC target genes." (PMID 28187001, 2017). "Furthermore, the participation of menin in c-Jun activation and its suppression by the MYC protein suggest that mutations in MEN1 and MAX may play a certain role in paraganglioma development." (PMID 28187001, 2017). "We successfully transduced primary paraganglioma tumour cells with a lentiviral construct, using the proven strategy of c-MYC¬T58A (c-MYC) controlled by a Tet-On doxycycline-inducible expression system." (PMID 41881005, 2026).
parathyroid tumor (2 papers, 2007 to 2019). "We speculate that ATAD2 could link E2F and MYC pathways and contribute to parathyroid tumor development." (PMID 30832348, 2019). "MYC, a direct target of the Wnt/β-catenin signaling pathway in colorectal cancer cells and established as the critical mediator of the early stages of intestinal neoplasia, was found to be overexpressed at the protein level in 79% of parathyroid tumors." (PMID 18044981, 2007). "Expression of the truncated LRP5 receptor was required to maintain the nonphosphorylated active β-catenin level, transcription activity of β-catenin, MYC expression, parathyroid cell growth in vitro, and parathyroid tumor growth in a xenograft severe combined immunodeficiency (SCID) mouse model." (PMID 18044981, 2007). "Maintained activity of endogenous β-catenin was found to be necessary for the expression of MYC and cyclin D1 (CCND1), as well as growth and survival of a unique human parathyroid tumor cell line." (PMID 18044981, 2007).
penile carcinoma (2 papers, 2013 to 2015). "This is further strengthened by the observation that there is a significant difference, not only in the expression but also in the co-localization of c-MYC and CD1 in penile carcinoma samples compared to controls." (PMID 25901368, 2015).
pituitary tumor (2 papers, 2020 to 2023). A benign or malignant neoplasm affecting the pituitary gland. "Additionally, c-MYC was overexpressed in pituitary tumors that were classified as aggressive, larger in size, and diagnosed at a younger age." (PMID 37104368, 2023). "As all non-functioning PitNETs (GTs and sCTs) were macroadenomas, while some functioning PitNETs (fCTs and STs) were microadenomas, the effect of E2F1 on the growth and invasiveness of pituitary tumours could be mediated by its interaction with MYC and miR-17-5p." (PMID 32316225, 2020).
Pleural effusion (2 papers, 2022 to 2025). The presence of an excessive amount of fluid in the pleural cavity. "Gains for YES1, encoding a SFK, and MYC genes were observed both in the pericardial biopsy and the pleural effusion samples." (PMID 35199053, 2022). "Diagnostic thoracentesis with immunophenotyping of the pleural effusion revealed immunoglobulin heavy chain (IGH) gene (14q32.33) and myelocytomatosis (MYC) oncogene (8q24.21) rearrangements, consistent with BL." (PMID 41503330, 2025). "In this case, the diagnosis was achieved not from the resected mass but through the cytological analysis of peritoneal and pleural effusions, which rapidly identified malignant lymphoid cells with MYC translocation." (PMID 41503330, 2025). "At whole exome sequencing analysis, YES1 and MYC amplifications were observed both in the pericardial biopsy and the pleural effusion samples collected at brigatinib and lorlatinib progression, respectively." (PMID 35199053, 2022). "An in-depth allele-specific copy number analysis of the pleural effusion sample revealed a complex genomic landscape and highlights a strong copy-aberrant loss of heterozygosity of YES1 gene and a MYC allele-specific gain." (PMID 35199053, 2022).
pleural mesothelioma (2 papers, 2022 to 2025). A neoplasm that arises from the mesothelial cells of the pleura. "In pleural mesothelioma, MYC expression is often upregulated." (PMID 41148814, 2025).
pterygium (2 papers, 2020 to 2021). A wedge-shaped fibrovascular lesion arising from the bulbar conjunctiva and extending to the cornea. "We found that genes encoding transcription factors MYC, KLF4, POU5F1 and PITX1 were upregulated in pterygium." (PMID 34769520, 2021). "MYC was moderately upregulated in both pterygium-E and pterygium-NE." (PMID 34769520, 2021). "There are 6 genes that are highly expressed in pterygium, MYC, CDH2, CCNB1, RELN, RB1, and ERBB4." (PMID 33299863, 2020). "In the comparison between pinguecula and pterygium subgroups, IPA predicted activation of pathways controlled by MYC, TP63 and KLF4 upstream regulators, which control epithelial cell fate." (PMID 34769520, 2021). "This analysis suggests an expansion of cells from the corneal limbal epithelial compartment in pterygium, and identifies KLF4, MYC and POU5F1 and PITX1 as specifically involved." (PMID 34769520, 2021). "Comparing pinguecula and pterygium, IPA predicted activation of pathways controlled by upstream regulators TP63, MYC and KLF4, transcription factors that control epithelial cell fate." (PMID 34769520, 2021). "We presume that the LINC00472 network might function in pterygium via the FOXM1 PATHWAY, especially through the regulation of CCNB1, MYC, ERBB4, RELN, RB1, and CDH2 in the ceRNA network." (PMID 33299863, 2020).
Salmonella Infections (2 papers, 2018 to 2023). Infections with bacteria of the genus SALMONELLA. "Interestingly, our SILAC results revealed that several members of the Rho GTPases network (CDC42, FAS, and MYC) underwent dynamic acetylation following Salmonella infection." (PMID 36812247, 2023).
sickle cell anemia (2 papers, 2017 to 2023). "Lineage-specific targeting of MYC in these diseases could potentially be achieved by taking advantage of these enhancer regions, as is currently being pursued, for example, in sickle cell disease by targeting an erythroid-specific enhancer of BCL11A40,41." (PMID 37400441, 2023).
synovial sarcoma (2 papers, 2016 to 2020). "Shen and colleagues examined 32 cases of limb synovial sarcoma immunohistochemically and revealed a significant association of c-MYC expression with poor patient prognosis." (PMID 32429395, 2020). "We previously revealed the significant association of poorly differentiated synovial sarcoma with the expression of MYC." (PMID 32429395, 2020). "We found that synovial sarcoma HS-SY-II cells with active Wnt target gene expression were highly dependent on MYC gene expression for proliferation." (PMID 32429395, 2020). "A high degree (>2.0-fold) of MYC oncogene amplification is known to be infrequent in synovial sarcoma." (PMID 32429395, 2020). "This marked downregulation of MYC was also observed in other synovial sarcoma cell lines." (PMID 32429395, 2020). "NCB-0846 induced apoptotic cell death in synovial sarcoma cells through blocking of Wnt target genes including MYC, and oral administration of NCB-846 induced regression of xenografts established by inoculation of synovial sarcoma cells." (PMID 32429395, 2020).
tauopathy (2 papers, 2019 to 2022). Neurodegenerative disorders involving deposition of abnormal tau protein isoforms (tau proteins) in neurons and glial cells in the brain. "Use of the NetDecoder informatics algorithm identifies key upstream biological targets, including MYC and EGFR, underlying the transcriptional and splicing changes in the protected compared to tauopathy mice." (PMID 31875547, 2019). "Thus, to discriminate the two tauopathies, we hereby propose JUN(B,D)HIGH, FOS(L1,L2)HIGH as well as the involvement of DUX4, KLF5, MAX::MYC, PAX6, and PPARG to support the identity of CBD-originated astrocytes." (PMID 35976433, 2022). "Immunohistochemical analysis in postmortem brain tissue of individuals with the very rare 3R tauopathy Pick's disease revealed colocalization of AP-1 components such as FOS, JUN, and MYC with the disease-defining intraneuronal pTau deposits (Pick bodies) and neuronal cytoplasms." (PMID 35976433, 2022).
thoracic cancer (2 papers, 2018 to 2022). A primary or metastatic malignant neoplasm affecting the tissues of the thorax. "Several studies have confirmed that JQ1 attenuated fibrosis and inflammation resulting from radiation used in radiotherapy in thoracic cancer by suppressing BRD4, c-MYC, p65 NF-κB, and the COLII/TGF-β/SMAD pathway." (PMID 36613933, 2022). "Additionally, JQ1 suppressed BRD4, c-MYC, Collagen I, TGF-β, p-NF-κB p65, p-Smad2 and p-Smad3 expressions after irradiation, repressed proliferation and transdifferentiation of lung fibroblasts, and impaired clonogenic survival of thoracic cancer cells." (PMID 29343723, 2018).
Thymic tumors (2 papers, 2013 to 2021). "This study highlighted METTL3 as a tumor promoter in Thymic tumors and c-MYC as a promising target to be exploited for the treatment of TET." (PMID 34530916, 2021). "Moreover, we evaluated whether METTL3 and its downstream target c-MYC may represent powerful targets to improve the treatment of thymic tumors." (PMID 34530916, 2021). "Notch1 transcript, activated NICD and downstream effectors of NOTCH1 signaling, including MYC and HES1, are all expressed at high levels in R26PR-derived thymic tumors." (PMID 24046360, 2013).
tubular adenocarcinoma (2 papers, 2010 to 2013). An infiltrating adenocarcinoma in which the malignant cells form tubular structures.
Uterine leiomyoma (2 papers, 2018 to 2022). The presence of a leiomyoma of the uterus. "We could confirm our previous result that PTSMT have higher expression levels of MYC than uterine and non-uterine leiomyomas." (PMID 29881541, 2018). "As could be expected from our previous results on uterine leiomyomas and PTSMT, MYC proto-oncogene, bHLH transcription factor (MYC) transcripts were significantly higher in PTSMT than in non-uterine visceral leiomyomas." (PMID 29881541, 2018).
uveitis (2 papers, 2025). An inflammatory process affecting a part of or the entire uvea. "Further experiments based on EAU showed that MYC regulates the effector T cell response in uveitis by regulating the collaboration between PI3K‐AKT‐FOXO1 signaling and glycolysis." (PMID 40586758, 2025). "Mechanically, inhibiting MYC disrupts the glycolysis‐PI3K signaling circuit to curb the effector T cell response in uveitis." (PMID 40586758, 2025). "Thus, our study indicated that MYC controls the effector T cell response in uveitis by regulating the glycolysis‐PI3K positive feedback circuit." (PMID 40586758, 2025). "Integrated single‐cell transcriptomic and metabolomic analyses reveal that MYC‐driven glycolysis activates the PI3K‐AKT‐FOXO1 pathway, disrupting Th17/Treg balance and promoting uveitis." (PMID 40586758, 2025). "Meanwhile, the MYC expression in T cells from patients with BU was upregulated in nearly all T cell subsets compared to BD without uveitis and the HC group." (PMID 40586758, 2025).
vascular tumor (2 papers, 2012 to 2022). "We hypothesize that this molecular process is frequent in AS, at least in those tumors carrying an amplification of MYC, and may play a crucial role in the tumorigenesis of such vascular tumors." (PMID 22383169, 2012). "The high incidence of MYC amplification in secondary AS and its occurrence in a subset of primary AS raises the question of its functional role in the tumorigenesis of these highly aggressive vascular tumors." (PMID 22383169, 2012). "The role of MYC in angiogenesis may be of particular importance in vascular tumors, such as AS." (PMID 22383169, 2012). "We profiled miRNA expression in 16 AS (eight with MYC amplification and eight without MYC amplification) and two other vascular tumors using deep sequencing of small RNA libraries." (PMID 22383169, 2012). "Therefore, we compared the expression of these two genes in AS with (n = 13) and AS without (n = 12) MYC amplification, other vascular tumors (n = 2), and WD/DDLPS (n = 4) by qRT-PCR." (PMID 22383169, 2012).
acral melanoma (1 paper, 2022). "In our study, the most common CNVs in mucosal and acral melanoma was MYC amplification, consistent with previous study in Asian patients." (PMID 35688842, 2022). "Although the role of MYC in the development and progression of mucosal and acral melanoma remains to be further studied, MYC may act as a new therapeutic target for the treatment of mucosal and acral melanoma with the application of effective inhibitors." (PMID 35688842, 2022). "NBN followed MYC also had a high CNVs rate in mucosal and acral melanoma." (PMID 35688842, 2022).
adrenal cancers (1 paper, 2023). A carcinoma involving a adrenal gland. "The higher rate of PKA-activating alleles in adrenal cancers allowed a more robust comparison, identifying multiple upregulated Hallmark Gene Sets, including MYC Targets V1 and V2." (PMID 36692000, 2023).
adrenal neoplasms (1 paper, 2023). "Nevertheless, data indicate that the embryogenic origin of the cells and the associated differentiation status influenced by HIF and MYC may contribute decisively to the phenotype of adrenal neoplasms." (PMID 37361539, 2023).
adrenocortical tumors (1 paper, 2021). "This is in conformity with previously published data that shows low MYC expression in adrenocortical tumors." (PMID 34572898, 2021).
anaplastic astrocytoma (1 paper, 2017).
aneurysm (1 paper, 2021). Bulging or ballooning in an area of an artery secondary to arterial wall weakening. "Moreover, aneurysm samples showed upregulation of genes involved in mitochondrial uncoupling and glycolytic rewiring (UCP2, HIF1A, and MYC)." (PMID 33709773, 2021).
Anterior polar cataract (1 paper, 2018). "Our data demonstrated that upregulation of MYC mRNA was detected in human PCO attached LECs and the LECs obtained from patients with anterior polar cataracts, which indicated that MYC was involved in the development of PCO." (PMID 29977916, 2018). "Furthermore, upregulation of MYC mRNA and EZH2 mRNA was detected in the LECs obtained from patients with anterior polar cataracts compared with patients with nuclear cataracts." (PMID 29977916, 2018).
Aortic dissection (1 paper, 2023). Aortic dissection refers to a tear in the intimal layer of the aorta causing a separation between the intima and the medial layers of the aorta. "In addition, MYC signaling participated in vascular smooth muscle cell (VSMC) dysfunction, vasoconstriction, and vascular remodeling in aortic dissection, and was increased in TAAD." (PMID 37283588, 2023).
autoimmune hepatitis (1 paper, 2022). Hepatitis caused by autoantibodies. "Thus, the key target genes for autoimmune hepatitis treatment mainly included AKT1, IL6, VEGFA, CASP3, JUN, MYC, etc.." (PMID 36558908, 2022).
autosomal recessive polycystic kidney disease (1 paper, 2023). An inherited disorder characterized by the development of cysts affecting the collecting ducts. "However, the role of MYC activation in the initiation and progression of autosomal recessive polycystic kidney disease (ARPKD; MIM#263200) remains incompletely understood." (PMID 38125876, 2023).
benign monoclonal gammopathy (1 paper, 2019). Conditions characterized by the presence of M protein (Monoclonal protein) in serum or urine without clinical manifestations of plasma cell dyscrasia. "Bergsagel and colleagues generated a mouse model of MM (Vk*MYC) under the C57bl/6 genetic background with sporadic c-Myc activation in germinal center B cells, resulting in the development of benign monoclonal gammopathy, a mouse equivalent to MGUS, which then progresses to MM." (PMID 31277689, 2019). "In this study, we demonstrate that glyphosate induces benign monoclonal gammopathy (mouse equivalent to MGUS in human) in WT mice and promotes MM progression in Vk*MYC mice." (PMID 31277689, 2019).
bile duct cancer (1 paper, 2023). "Furthermore, MYC can induce HMGA1 and TRIP13 transcription by bile duct cancer cells to enhance bile duct cancer cell migration, proliferation, invasion, dryness, and epithelial–mesenchymal transition (EMT)." (PMID 37504265, 2023).
bile duct sarcoma (1 paper, 2022). A sarcoma that involves the bile duct.
Chagas disease (1 paper, 2016). A parasitic infection caused by Trypanosoma cruzi. "The MYC/SP1 transcription factors that regulate hypoxia and oxidative/inflammatory stress were predicted to be key targets in the context of control of Chagas disease severity." (PMID 26919708, 2016).